TNF (tumor necrosis factor)
Diseases named in the same sentence as TNF in open-access papers (continued):
Sharing a sentence is not in itself a finding about the gene and the disease.
Arthritis (continued). "Both the number of TNF-α+ monocytes/macrophages and the number of TNF-α+ neutrophils were significantly (p = 0.001 and p = 0.019) and positively correlated with arthritis score." (PMID 32966314, 2020). "We note that the GM-CSF–CCL17 signaling axis can be downstream of TNF and that CCL17 has recently been postulated as a therapeutic target in other forms of arthritis." (PMID 32765525, 2020). "Thus, RIP1 may be activated by TNF to promote arthritis in this mouse model." (PMID 31101885, 2020). "In an in vivo study, CTLA-4Ig suppressed the generation of large amounts of TNF-α and IFN-γ by splenocytes from DBA/1 mice with glucose-6-phosphate isomerase-induced arthritis." (PMID 33322156, 2020). "We have simulated induced arthritis in laboratory mice using CFA, which induces the release of TNFα into tissues, to demonstrate that peptide 17.1 exhibits a protective effect on articular cartilage and bone tissues." (PMID 32093269, 2020). "TGs, which derived from botanical materials, exhibits immune-suppressive functions, and also attenuates inflammation and arthritis through reducing PGE2 production and levels of IL-1α, IL-1β, TNF-α and IL-6." (PMID 32503513, 2020). "Brazilin was also found to decrease the expression of TNFα in mice with type-II collagen-induced arthritis and to decrease the expression of COX2 and TNFα, and inhibit ERK/NFkB signaling in RANKL-stimulated RAW264.7 cells." (PMID 32986377, 2020). "These herbs diminish the expression of inflammatory mediators, such as IL-1, IL-6, TNF-α, PGE2, and COX-2, via modulation of NF-κB activation and kinase activity in in vitro and in vivo arthritis models." (PMID 33126603, 2020). "CD163+ macrophages expressed a pro-inflammatory profile of biomarkers (activin A, TNFα, and MMP-12) in synovial tissue from all arthritis subtypes studied, while in paired samples of synovial fluid only activin A levels were widely detected." (PMID 33679701, 2020). "On the one hand, some pro-inflammatory cytokines, such as tumor necrosis factor-α (TNF-α), interleukin (IL)-6, and IL-1, facilitate the development of arthritis." (PMID 32958016, 2020). "The significant decrease in the levels of TNF-α, IL-1β, and IL-6 confirmed a positive effect of rhoifolin on alleviating inflammation in CFA-induced arthritis." (PMID 32401927, 2020). "The feeding of arthritic mice with food-based Lactococcus engineered to express CFA/I fimbriae prevents arthritis by inducing CD39+ Tregs to secrete TGF-β and IL-10 and thus inhibit TNF-α production and neutrophil influx into the joints." (PMID 33442384, 2020). "TNF-α, IL-17, IL-6, and DKK-1 serum levels were increased, and obestatin and sclerostin serum levels were decreased in the arthritis group compared to the control group." (PMID 32659877, 2020). "TNF-α was significantly increased in MSU crystals-induced gouty joints of mice and was positively correlated with the severity of arthritis." (PMID 33149752, 2020). "Together these studies demonstrate that in arthritis, local 11β-HSD1 expression and activity is under the regulatory control of the pro-inflammatory microenvironment, driven by TNF-α and IL-1β." (PMID 32963891, 2020). "Since effector inflammatory CD4+ T lymphocytes are critical in arthritis progression, we also examined the frequencies of IFN-γ+CD4+ T cells and TNF+CD4+ T cells at two time points of disease development (day 42 and day 95)." (PMID 33072101, 2020). "GNE684 reduced arthritis in wild-type mice to a similar extent, with protection comparable to that seen using TNFR2-Fc to block signaling by TNF." (PMID 31101885, 2020). "Oral intake of a mixture of Acacia catechu water extract and Morus alba root bark ethanol extract (50 mg/kg BW) has anti-inflammatory (TNF-α and IL-1β), collagenase (MMP-13) inhibitory, and articular cartilage protective activities in MIA-induced arthritis." (PMID 33371279, 2020).
Arthritis (continued). "As is well known, TNF-α is one of the important pro-inflammatory cytokines conducive to RA-FLS survival and progressive arthritis in RA pathology." (PMID 32499694, 2020). "In summary, stimulation with TNFα, IL‐6 and MIF lead to cytokine-mediated cartilage degradation, a key feature of arthritis." (PMID 33374446, 2020). "Rats treated with UP1306 showed statistically significant improvements in arthritis severity markers, including uCTX-II (91.4% vs. collagen-induced arthritis (CIA)), serum IL-1β, TNF-α, and IL-6 levels as well as synovial MMP-13." (PMID 30691120, 2019). "To confirm the therapeutic effect and mechanism of PL on OA, we established an animal model of arthritis by intra-articular monoiodoacetate (MIA)-injection and a cellular model of arthritic chondrocytes by TNF-α treatment." (PMID 31089001, 2019). "Current treatment of RA aims to block pro-inflammatory effector cytokines such as TNFα and IL6, which are produced in the synovium and trigger arthritis." (PMID 31001257, 2019). "In this study, we found that treatment of the collagen-induced arthritis (CIA) mice with CGA significantly attenuated arthritis progression and markedly inhibited BAFF production in serum as well as the production of serum TNF-α." (PMID 31240234, 2019). "Patients with arthritis/arthralgia received significantly more often 5-ASA, antibiotics, steroids, immunomodulators and anti-TNF." (PMID 31039159, 2019). "This case suggests that with exacerbation of arthritis during gouty arthritis, coexistence with other pathologies such as peripheral spondyloarthritis should be considered, and early intensive treatment including tumor necrosis factor inhibitors may be necessary." (PMID 31577714, 2019). "The presence of the cytokines MCP-1, TNF and INF-γ serum, as well as MCP-1 in the muscle, indicate the action of macrophages in target tissues of infection, which makes this cell and MCP-1 important elements common in therapy of arthritis caused by RRV, CHIKV and MAYV." (PMID 31050676, 2019). "QZTB suppressed the serum IL-1β (P < 0.01) and TNF-α (P < 0.001) levels in the MSU crystal-induced rats, suggesting that QZTB can inhibit NLRP3 pathways contributing to arthritis in this acute gout model." (PMID 31885675, 2019). "In the present study, we found that CGA markedly ameliorated arthritis progression in CIA mice in a dose-dependent manner, which was accompanied with the inhibition of BAFF production as well as the decrease of TNF-α." (PMID 31240234, 2019). "In regions of inflammation in arthritis and tumors, vascular endothelial cells are activated by inflammatory cytokines, such as TGF-α and TNF." (PMID 31426531, 2019). "There is a synergetic effect between TNF, IL-1ß, IL-17, and S100A8 leading to induction of erosive MMPs and exaggeration of cartilage erosion during arthritis." (PMID 30828327, 2019). "The anti-arthritis mechanism of action for ASHW was established through the suppression of pro-inflammatory cytokines such as IL-1β, IL-6, TNF-α; and upstream regulator, NF-κB." (PMID 31142786, 2019). "According to several clinical trials, baricitinib has shown to improve arthritis symptoms not only in DMARD-naive patients, but also in patients with an inadequate response to MTX, csDMARDs, or TNF inhibitors." (PMID 31382539, 2019). "We found that expression levels of IL-1β, IL-6, TNFα, CCL3 and MCP-1 molecules were significantly (p < 0.05) increased after induction of arthritis in the bone marrow of KLF2+/− mice compared to KLF2+/+ mice." (PMID 31426355, 2019). "SM significantly improved arthritis symptoms; increased the level of OPG; inhibited the levels of TNF-α, IL-1β, CRP, ATX, and LPA; and alleviated cartilage and bone injury." (PMID 31001354, 2019). "In the adjuvant-induced arthritis model, mPEG-SC20K-HM-3 (PEG-HM-3) treatment decreased the levels of IL-6 in spleens, TNF-α, cluster of differentiation 31 (CD31) and CD105 in the joint cavity by immunohistochemistry analysis." (PMID 30201867, 2018).
Arthritis (continued). "These drugs retain endogenously generated TNF in vitro, and in vivo the F4/80-directed MYSTI protects against LPS/D-Gal lethal toxicity and was also active in the anti-collagen antibody transfer arthritis model." (PMID 29751683, 2018). "Consistent with the results of arthritis score, the pathological score of knee joint was significantly reduced in the UC-MSC transplantation group (P < 0.01) and the anti-TNF-α-treated group (P < 0.05) compared with the control and ZA group." (PMID 29853911, 2018). "The strong TNF-α induction by RNA-IC is interesting since TNF-α plays a critical role in several SLE disease manifestations, such as nephritis, skin lesions, and arthritis, all characterized by tissue deposition of ICs." (PMID 30355354, 2018). "Considering the efficacy of anti-TNFα agents in the treatment of RA, the fact that TRPA1 appears to be downstream of TNFα in the pathology of arthritis positions it as a potentially important drug target." (PMID 30326593, 2018). "The arthritis score was significantly reduced in the UC-MSC transplantation and anti-TNF-α-treated CIA groups, compared with control mice (P < 0.001)." (PMID 29853911, 2018). "CKD-L decreased the arthritis score in CIA, reduced the expression of TNF and IL-1β, and increased the expression of IL-10 in PBMC from RA patients." (PMID 28673326, 2017). "CKD-L, a selective HDAC6 inhibitor, decreased the arthritis score in CIA, reduced the expression of TNF and IL-1β, and increased the expression of IL-10 in PBMC from RA patients." (PMID 28673326, 2017). "In synovial fibroblasts from arthritis patients, HDAC1 siRNA enhanced TNFα-induced MMP-1 expression, whereas HDAC4 was identified as a negative regulator of MMP-1 expression." (PMID 28596772, 2017). "Our data demonstrated that CKD-L, a selective HDAC6 inhibitor, decreased the arthritis score and protected against joint destruction in the CIA model, and reduced the expressions of TNF and IL-1β, and increased the expression of IL-10 in PBMC from RA patients." (PMID 28673326, 2017). "TNFKi induced the production of anti-TNF-α polyclonal antibodies and alleviated arthritis in two experimental models of arthritis, CIA and CAIA, which confirms the effective neutralization of TNF-α." (PMID 29184553, 2017). "Since the immune function of CFA, the serum levels of IFN-γ, IL-6, IL-17A and TNF-α in PDCD5 tg mice and their arthritis control were significantly increased, however the production of pro-inflammatory cytokines in PDCD5 tg mice were relatively inhibited." (PMID 29228993, 2017). "In order to further elucidate possible actions of platelet concentrates in arthritis, we have investigated the effect of PRGF on an in vitro model for inflammatory arthritis using TNF-α-stimulated K4IM cells." (PMID 29348703, 2017). "Our aim was to use TNF-α-overexpressing mice to clarify the intersection of TNF-α, citrullination, PAD4, arthritis, and lung inflammation." (PMID 27450561, 2016). "This study aimed to investigate the effect of barbatimão and 11 other species on the production of tumor necrosis factor-alpha (TNF-α) in lipopolysaccharide- (LPS-) stimulated THP-1 cells, as well as their anti-arthritis activity." (PMID 27867403, 2016). "The inhibition of IL-17 also significantly reduced bone erosion in a mouse experimental arthritis model by reducing the levels of RANKL, IL-1, and TNF-α." (PMID 27169372, 2016). "Production of key cytokines IL-17 and TNF-α was significantly reduced in SKG Ptpn22−/− mice following arthritis induction compared with SKG mice." (PMID 27288531, 2016). "Recently, a new anti-TNF-α agent named TNFR-hyFc (TNFR with a hybrid Fc) showed a higher neutralizing activity and even a better protective effect in an arthritis model compared to Etanercept administration." (PMID 27824131, 2016). "Of interest at this time of arthritis, plasma IL-1β and MCP-1 levels are elevated in AIA like at day 11, but additionally TNF-α and MIP-1α increased." (PMID 26761790, 2016).
Arthritis (continued). "In the absence of intra-articular injection of mBSA the levels remain low, whereas if arthritis is triggered by intra-articular injection of mBSA, the serum levels of IL-6, IL-12, IL-17, IFN-γ and TNF increase rapidly again." (PMID 26512984, 2015). "Using our selective mouse TNFR1 inhibitor in the collagen-induced arthritis model, we demonstrated different effects when inhibiting TNFR1 compared to pan-TNF-α inhibition with mouse TNFR2-Fc." (PMID 26352810, 2015). "CIHH pretreatment has a protective effect against collagen-induced arthritis in rat through down-regulation of HIF-1α and NF-κB, inhibition of inflammatory cytokines TNF-α and IL-17, and balance in CD4/CD8 and Th1/Th2 T lymphocytes." (PMID 25861246, 2015). "Mazzon and colleagues also reported that intraperitoneal injection of the adenosine A2AR agonist, CGS21680, resulted in relief of arthritis symptoms in CIA mice and a decrease in release of TNF-α and IL-1β, pointing to a role of A2AR in CIA." (PMID 25784951, 2015). "In arthritis models, CBD blocks its progression, decreasing collagen II-specific proliferation and IFN-γ production, as well as decreasing the release of TNF-α by synovial cells." (PMID 25517414, 2014). "γ-tocotrienol significantly reduced the arthritis-induced changes in body weight, CRP, TNF-α, SOD and the total GSH levels." (PMID 24940448, 2014). "Recently, biological agents, represented by anti-tumor necrosis factor (TNF) monoclonal antibodies (mAb), have been used widely to improve arthritis and to inhibit bone destruction." (PMID 25115332, 2014). "In another study using the CIA model of arthritis, PGT treatment reduced the expression of COX-2, IFN-γ, and TNF-α." (PMID 23476694, 2013). "It is known that the recently available biologic drugs neutralizing RANKL and TNF-α, key cytokines in CAVD pathogenesis, are having a great success in the treatment of osteoporosis and arthritis, respectively." (PMID 24307884, 2013). "The anti-arthritis effects of melittin, an HBV constituent, are suggested to be decrease in COX-2 and phospholipase A2 expression and decline in the levels of TNF-alpha, IL-1, IL-6 and ROS." (PMID 24330637, 2013). "Previous studies have demonstrated a central role for TNF in RA, and early preclinical studies indicated that inhibition of TACE was beneficial for patients with arthritis." (PMID 24314260, 2013). "Interestingly, blockade of TNFα reduces joint inflammation while inhibition of IL-1β protects against cartilage degradation in mouse arthritis models, suggesting the latter may be an attractive molecular target in the development of disease-modifying therapies." (PMID 23889808, 2013). "The pro-inflammatory mediators, elevated TNF-α and VEGF contribute largely to the pathogenesis of RA and in experimental arthritis models." (PMID 24112447, 2013). "Secretion of both IL-6 and TNFα was dose-dependent, with maximal secretion detected at 1 μg/ml of S100A9, a concentration found in the synovial fluid of arthritis patients." (PMID 23029038, 2012). "DTH-arthritis is dependent on CD4+ cells for induction and can be successfully treated with TNFα-blocking biologics and dexamethasone." (PMID 22676339, 2012). "TMI-1 has been successfully used in mouse models of arthritis and kidney diseases to target and inhibit ADAM-17-mediated TNFα (Tumor Necrosis Factorα) and TGFα (Transforming Growth Factorα) release, respectively." (PMID 23028451, 2012). "We showed that arthritis was characterized by an early transcriptional activation of the chemokine MCP-1, the proinflammatory cytokines IL-1β, IL-6, and TNFα, and the angiogenic factor VEGF in synovial tissue." (PMID 22414623, 2012). "All compounds produced excellent inhibition of TNF and IL1 resulting in improved animal survival in a peritonitis model of septic shock and inflammation in an arthritis model." (PMID 22348221, 2012).
Arthritis (continued). "The levels of TNF-α and IFN-γ were raised in untreated arthritis to 3.1 and 10.7 ng mL−1, and after Lyprinol treatment were decreased to 1.71 and 3.0 mg mL−1, respectively." (PMID 19383840, 2011). "Mice lacking TTP develop an inflammatory syndrome characterized by arthritis, dermatitis and cachexia as a consequence of enhanced stability of TNF-α mRNA and the resulting excess TNF-α production." (PMID 20701773, 2010). "In murine AIA, significant and temporal changes in cytokines (IL-1β, TNFα, IFN-γ, IL-6) and factors that govern extracellular matrix turnover (MMP-3, MMP-13, TIMP-1) occur during the acute phase, Days 1 to 3 after arthritis induction." (PMID 20307272, 2010). "In contrast, the TNFα mRNA expression level in arthritic joints tended to increase at day 7, though insignificantly, in mice with GPI-induced arthritis." (PMID 19660107, 2009). "Increased local levels of IL-1 β, IL-6, TNF-α, MIP-1α, and MIP-2 accompanied the more severe arthritis in IL-4−/− mice." (PMID 19606256, 2009). "This study sought to demonstrate a long-lasting therapeutic effect on established arthritis of an active immunotherapy to human (h) TNF-α and to evaluate the long-term consequences of an endogenous anti-TNF-α response." (PMID 20030816, 2009). "To explore the relevance of the therapeutic effect of anti-TNFα mAb on TIARP expression, we evaluated TIARP expression after injection of anti-TNFα mAb in mice with GPI-induced arthritis." (PMID 19660107, 2009). "Based on previously reported results, anti-TNFα, anti-IL-1, or anti-RANKL therapy was begun on day 4 after initial onset of arthritis, when paw swelling was at or near its peak in both CIA and AIA rats." (PMID 20003323, 2009). "Palucka and colleagues reported recently that blocking TNF signaling increases the production of IFNα by plasmacytoid dendritic cells and induces an IFN signature in the blood of arthritis patients." (PMID 19121222, 2009). "For example, we detected specific TNF-α-induced molecules in spleen and joints of mice with GPI-induced arthritis by Genechip analysis (Matsumoto and Inoue, unpublished data)." (PMID 18534002, 2008). "TNF-α and IL-6 play an important role in GPI-induced arthritis, whereas IFN-γ appears to function as a regulator of arthritis." (PMID 18534002, 2008). "In the present study, we showed augmented arthritis development in RP105-/- mice, with an increased production of IFN-γ and TNF-α from spleen cells in response to CII." (PMID 18847495, 2008). "Large amounts of TNF-α and IFN-γ and small amounts of IL-2 and IL-6 were produced by splenocytes from mice with GPI-induced arthritis." (PMID 18534002, 2008). "In advanced arthritis, the number of cells with cytoplasmic HMGB1 expression was quantitatively comparable to that of cells expressing TNF and IL-1β." (PMID 17397533, 2007). "Previous studies also reported a strong involvement of the TNF/TNFR pathway because CIA only developed with a reduced disease incidence, and the severity and neutralization of TNF led to the prevention of arthritis." (PMID 15987490, 2005). "Taking into consideration increased levels of TNF-α in patients with RA and the obvious effect of TNF-α neutralization for the alleviation of arthritis, our finding of a low incidence of antibodies against TIMP-3 is unexpected." (PMID 16207317, 2005). "To explore the mechanism of the RA and the function of BZXD, we make the collagen-induced arthritis rat and treated with BZXD, then detect the level of TNF-α and IL-1β in plasma at various interval." (PMID 23674954, 2005). "It was found that HC could reduce foot swelling in CIA rats, lower the arthritis index, and decrease the secretion of MMP-2, MMP-3, TNF-α, and IL-6." (PMID 41508102, 2026).